MIOS (meiosis regulator for oocyte development)
Description:
As a component of the GATOR2 complex, functions as an activator of the amino acid-sensing branch of the mTORC1 signaling pathway. The GATOR2 complex indirectly activates mTORC1 through the inhibition of the GATOR1 subcomplex. GATOR2 probably acts as an E3 ubiquitin-protein ligase toward GATOR1. In the presence of abundant amino acids, the GATOR2 complex mediates ubiquitination of the NPRL2 core component of the GATOR1 complex, leading to GATOR1 inactivation. In the absence of amino acids, GATOR2 is inhibited, activating the GATOR1 complex. Within the GATOR2 complex, MIOS is required to prevent autoubiquitination of WDR24, the catalytic subunit of the complex. The GATOR2 complex is required for brain myelination (By similarity).
Synonyms: FLJ20323; MIO; Sea4; Yulink
Tractability: PROTAC: ubiquitination databases record sites on it; its protein half-life has been measured.
Gene: Protein-coding gene on chromosome 7 (7,566,823 to 7,609,140, forward strand). Ensembl gene ENSG00000164654.
Subcellular location: Lysosome membrane
Subcellular location (Human Protein Atlas): Nucleoplasm; Cytosol
Pathways (Reactome):
Cellular responses to stimuli: Amino acids regulate mTORC1
Gene Ontology:
Molecular function: protein binding
Biological process: cellular response to amino acid starvation; cellular response to nutrient levels; positive regulation of TORC1 signaling; protein-containing complex localization; negative regulation of TORC1 signaling; oligodendrocyte differentiation; oligodendrocyte progenitor proliferation; central nervous system myelin formation
Cellular component: cytosol; GATOR2 complex; lysosomal membrane; nucleoplasm; cytoplasm
Genetic constraint (gnomAD): Loss-of-function variants: 44 observed, 89.61 expected, observed/expected ratio (o/e) 0.49, 90% interval 0.38 to 0.63. The upper end of that interval is the gene's LOEUF score, 0.63, which puts it in group 2 of 6, group 1 being the genes least tolerant of losing a copy. Missense variants: 918 observed, 1,033 expected, observed/expected ratio (o/e) 0.89, 90% interval 0.84 to 0.94. Synonymous variants: 370 observed, 353.75 expected, observed/expected ratio (o/e) 1.05, 90% interval 0.96 to 1.14.
Homologues: Orthologues: chimpanzee MIOS (100% identical), dog MIOS (99% identical), macaque MIOS (99% identical), guinea pig MIOS (99% identical), pig MIOS (99% identical), rabbit MIOS (98% identical), mouse Mios (98% identical), rat Mios (98% identical), tropical clawed frog mios (88% identical), zebrafish mios (82% identical), Drosophila melanogaster mio (32% identical), Caenorhabditis elegans F39C12.1 (30% identical).
Diseases named in the same sentence as MIOS in open-access papers:
MIOS is named in the same sentence as 7 diseases in open-access papers, as found by Europe PMC text mining. Sharing a sentence is not in itself a finding about the gene and the disease. The quoted sentences say what the papers report.
Alzheimer disease (1 paper, 2024). A progressive, neurodegenerative disease characterized by loss of function and death of nerve cells in several areas of the brain leading to loss of cognitive function such as memory and language. "The three top hits, HO-1 (heme oxygenase-1), MIOS, and SYNE2, exert diverse functions, yet each has been linked to neurodegeneration and Alzheimer’s disease." (PMID 37919601, 2024).
tumor (2 papers, 2021 to 2025). "Interestingly, three members of the GATOR2 complex (WDR59, MIOS, SEH1L) were found in our negative hits, underscoring the importance of these characterized GATOR2 components in promoting tumor growth in TNBC." (PMID 34031411, 2021).
MIOS also shares sentences with these, for which no sentence is quoted: cancer (3 papers); cardiac hypertrophy (1); glioblastoma (1); hepatocellular carcinoma (1); pulmonary arterial hypertension (1).